CD27 (CD27 molecule)
Diseases named in the same sentence as CD27 in open-access papers (continued):
Sharing a sentence is not in itself a finding about the gene and the disease.
cancer (continued). "The treatment effectiveness of cancer vaccines and immunotherapy can be improved by CD27 agonist antibodies, either alone or in combination with anti-PD1 antibodies." (PMID 35008645, 2021). "Similar to 4‐1BB, CD27 is targeted in clinical trials to enhance antitumor T‐cell immunity in cancer patients." (PMID 33180337, 2021). "The modulation of members of the tumor necrosis factor receptor family (TNFR) including CD40, OX40, and 4-1BB is also currently a focus of investigation, with amplification of CD27 signaling being explored for cancer immunotherapy." (PMID 32665635, 2020). "Our study showed that CD27 mRNA expression was lost in more than 98% of the 1103 CCLE cancer cell lines from 22 tissues (#2)." (PMID 31358815, 2019). "Regarding receptors, there exhibited a strong correlation with PD-1 and receptors including TIGIT, CTLA-4, LAG3, BTLA, ICOS, TNFRSF9, CD27 in most types of cancer." (PMID 30607140, 2018). "In cancer immunotherapies, agonistic antibodies that target T cell surface proteins, such as CD27, OX40 (CD134), and 4-1BB (CD137), have been used to enhance T cell function by increasing co-stimulation." (PMID 30073152, 2018). "Agonistic antibodies to 4-1BB, OX40 and CD27 that are immune-stimulatory are being tested as potential immunotherapies for cancer patients and the efficacy of anti-4-1BB pre-clinically has been shown to depend on TRAF2-mediated NF-κB activation." (PMID 25648675, 2015). "To address these concerns, we utilized a non-integrating RNA platform to engineer human T cells to express FRα-specific, CD27 CARs and tested their capacity to eliminate human FRα+ cancer." (PMID 26359629, 2015). "In vitro and in vivo preclinical data have provided the basis for continued development of 4-1BB, OX40, glucocorticoid-induced TNFR-related gene, herpes virus entry mediator, and CD27 as potential therapies for patients with cancer." (PMID 24855562, 2014). "Elevated T, including memory phenotype (CD27+), particularly in the cancer + treatment group, could be driven by the following possibilities, which need in-depth investigation." (PMID 40313772, 2025). "CD27 is also implicated in chronic viral infections such as HIV, where its persistent expression on T cells is associated with immune activation and eventual T cell dysfunction, reflecting features of exhaustion similar to those observed in cancer." (PMID 40484866, 2025). "Furthermore, we experimentally verified the difference in the mRNA expression of CD27 in some cancer cell lines and normal cell lines." (PMID 38169519, 2024). "The predictive significance of CD27 for pan-cancer was investigated utilizing several databases." (PMID 38169519, 2024). "More mechanistic insights may be gleaned from prospective studies of CD27 expression and immune cell infiltration in different cancer populations in the future." (PMID 38169519, 2024). "In addition, in the mRNA expression profile, we found a significantly higher expression of CD27 in DLBC that is different from other cancers." (PMID 38169519, 2024). "CD27 regulates multiple signaling pathways to influence cancer progression." (PMID 38169519, 2024). "In addition, CD27 synergistically upregulated several immune-related signaling pathways in four cancers, including antigen receptor-mediated signaling pathways, TCR signaling pathways, and chemokine signaling pathways." (PMID 38169519, 2024). "Therefore, our goal was to examine the predictive role of CD27 in the clinical prognosis of 33 cancer types and its functions in cancer progression, as well as explore the link between pan-cancer CD27 gene expression and immune infiltration." (PMID 38169519, 2024). "We used transcriptome sequencing data and contrast-enhanced computed tomography images of patients with SOC from The Cancer Genome Atlas (n = 339) and The Cancer Imaging Archive (n = 57) and evaluated the clinical significance and prognostic value of CD27 expression." (PMID 38909269, 2024).
cancer (continued). "These show that the CD27 has a dual role in the progression of certain cancers." (PMID 38169519, 2024). "Therefore, it is necessary to look at how TMB or MSI and CD27 expression are related to various cancer types." (PMID 38169519, 2024). "Additionally, we can see that immunological scores in the six cancers have a favorable connection with CD27 expression." (PMID 38169519, 2024). "In three cancers, including LAML, LGG, and UCEC, CD27 expression was linked favorably with TMB." (PMID 38169519, 2024). "TMB was negatively correlated with CD27 expression in eleven different cancers." (PMID 38169519, 2024). "Therefore, the effects of the CD27 in cancer were comprehensively evaluated by pan-cancer analysis, including regulation of immune invasion, TME, signal transduction, and prognosis." (PMID 38169519, 2024). "To test this hypothesis and to gain a better mechanistic understanding of the roles of soluble CD27 and EV-bound CD27, we performed a multicenter study including 232 patients with 466 blood specimens across 12 cancer types." (PMID 39511626, 2024). "Based on these findings, it appears that CD27 may influence cancer patients' prognoses by interacting with invading immune cells." (PMID 38169519, 2024). "Therefore, the activation of CD27 signaling is regarded as a potentially effective therapeutic anti-cancer strategy." (PMID 37545491, 2023). "In the current study, we aimed to evaluate whether CD27 co-stimulation could be restricted to epidermal growth factor receptor (EGFR)-positive cancer (EGFR+)." (PMID 37545491, 2023). "However, one obstacle of cancer immunotherapy is the exhaustion of T-cells, which was shown by the decrease in CD27 and CD127 on CD8+ T-cells upon ICI therapy in our current study." (PMID 37901220, 2023). "Furthermore, inhibition of Treg-expressed CD27 acts synergistically with PD-1-checkpoint inhibition to improve CTL-mediated immunity against solid tumors, suggesting that CD27 is a useful marker in cancer immunotherapy." (PMID 37182149, 2023). "CD27xEGFR’s FcR independence, relying on EGFR+ cancer cells to provide a CD27 cross-linking platform, could avoid these unwanted effects." (PMID 37545491, 2023). "In particular, the use of monoclonal antibodies—including Varliumab (anti-human CD27)—in cancer treatment has been studied in multiple clinical trials, but the anti-CD27 mAb has been produced only in CHO cells, and contamination and high cost are concerns when using CHO cells." (PMID 37615027, 2023). "Varlilumab, a CD27 agonistic antibody, showed promising efficacy in several cancers." (PMID 35742834, 2022). "Our data thus identify Treg-expressed CD27 as a potential target in cancer immunotherapy." (PMID 34423375, 2022). "In addition, exploiting the endogenous protein ligand CD27 as the antigen-recognition domain in CAR-T cells is a very promising development for CD70-positive cancers." (PMID 35053463, 2022). "Our work here suggests that blocking of CD27 selectively on Tregs might be a therapeutic strategy for immunotherapy of cancer in synergy with blockade of the PD-1 PD-L1 checkpoint." (PMID 34423375, 2022). "In cancer, immunological disease, and inflammatory disease, CD27 activates NF-κB." (PMID 34503105, 2021). "Cancer-specific Tscm or Tcm cells, which express CD27, CCR7, and CD62L molecules, may be the most clinically relevant subtypes for successful T cell-based immunotherapy." (PMID 34603332, 2021). "Similar to 4‐1BB, CD27 is also considered a promising target for cancer immunotherapy." (PMID 33180337, 2021). "In contrast, the expression of genes regulating immune cell trafficking (e.g., CXCL13, CXCL9, XCL2, CCL5), T-cell activation and clonal expansion (e.g., CD27, CD28, ICOS, IL21, IL2) were massively decreased in 9p21-loss tumors across multiple cancer types/subtypes." (PMID 34556668, 2021).
cancer (continued). "Combining a CD27 agonist antibody with PD-1/PD-L1 blockade has shown synergistic antitumor activity in preclinical models, which led to clinical studies of the combination in cancer patients." (PMID 32451681, 2020). "Various strategies have been proposed for targeting CD27 for cancer therapy." (PMID 30298117, 2018). "However, caution is required in terms of exploiting the immunoregulatory role of CD70/CD27 for cancer immunotherapy." (PMID 23840967, 2013). "Further preclinical studies are needed to evaluate whether this dualistic and context-dependent use of CD70/CD27 for cancer therapy is feasible." (PMID 23840967, 2013). "Based on the current evidence, we hypothesize that soluble CD27 functions as a predictive biomarker in ICI across multiple cancer types, while EV-bound CD27, despite playing an opposite immunological role, also functions as a predictive biomarker in this setting." (PMID 39511626, 2024). "Besides, the results showed the prognostic impact of CD27 across different cancers." (PMID 38169519, 2024). "Similarly, sCD27, which is strongly expressed in cancers, might interact with these CD27+CD70+ expressing MPs, thereby canceling out the benefits of transfusion." (PMID 36969173, 2023). "Furthermore, we identified that CD27 expression is negatively associated with cancer invasion signature (CIN25), indicating enforced CD27 expression in tumors may inhibit cancer invasion." (PMID 35874720, 2022). "The rationale behind these trials has been to study the impact of CD27 agonism alone as a T-cell co-stimulator as well as to determine if it functions in a synergistic manner in combination with checkpoint inhibitor therapy and cancer vaccines to improve antineoplastic response." (PMID 34630390, 2021). "Senescent T cells exhibit abnormal phenotypes, including downregulation of CD27, CD28, and upregulation of CD57, killer cell lectin-like receptor subfamily G, Tim-3, Tight, and cytotoxic T-lymphocyte-associated protein 4, which are tightly related to malignant tumors." (PMID 33168037, 2020). "Therefore, targeting the CD70/CD27 axis could be of great relevance in treating cancer types that currently lack effective treatment strategies." (PMID 31652572, 2019). "This study demonstrated poorer overall survival correlated with CD27 levels and identified that MM cells rely on the CD27–CD70 axis to evade immune surveillance, hence promoting cancer progression." (PMID 40597436, 2025). "Contrarily, CD27 played a detrimental role in other cancers, including UVM and GBM, in which patients whose CD27 expression was high had a lower chance of survival than those whose CD27 mRNA levels were low." (PMID 38169519, 2024). "And in preclinical models of several cancers such as LAML and GBM, CD27 targeting antibodies showed great efficacy 38-41." (PMID 38169519, 2024). "Therefore, targeting CD27 may offer significant opportunities to treat various cancers." (PMID 39105866, 2024). "Lastly, in concordance with previous literature, we observe a significant increase of CD27+ and CD8+ activated T cells in GATA6high-infiltrated stroma areas, displaying a similar significant trend for CD27+ T cells in infiltrated carcinoma areas." (PMID 38733987, 2024). "CD70 was found to be upregulated across many cancers, while CD70/CD27 expression correlated with Treg infiltration levels." (PMID 37345056, 2023). "The ARMG risk score showed significantly positive relation with immunoinhibitors TGFB1 and VTCN1, and was negatively related with immunostimulators CD27, CD28, CD40LG, CD80, ENTPD1 and ICOS in pan-cancer." (PMID 38090588, 2023). "CD4, Fibronectin, CD27, CD11c, and IDO1 were the protein markers from ‘immune-rich cancer cell islets’ and ‘surrounding stromal leukocyte’ regions linked with a significant hazard ratio and overall survival." (PMID 37046826, 2023). "In a pan-cancer analysis, CD70/CD27 signaling was, surprisingly, found to contribute to immune evasion, potentially through CD70-mediated Treg recruitment." (PMID 37345056, 2023).
cancer (continued). "Since immune checkpoint inhibitors (ICIs) have been a prominent topic in cancer treatment, the expression of eight ICIs (LAG3, HAVCR2, CD27, TNFRSF14, CTLA4, TMIGD2, TIGIT, and PDCD1LG2) were analyzed between groups in the study." (PMID 37405988, 2023). "Learning from the trials of the immune checkpoint inhibitor therapies, it is possible to design novel approaches targeting the IGM-type of cancer plasticity: early clinical examples are CD20, CD27/CD70, CD166, and IDO." (PMID 36754910, 2023). "On the other hand, the medium-expression group included TNFRSF18, TNFRSF4, CD27, and LAG3 and their expression levels varied significantly among the different cancer samples." (PMID 36157232, 2022). "Our results suggested that in most types of cancer, SERCA3 expression was distinctly related to immune checkpoints, such as TLR4, ICOS, CTLA-4, PDCD1, and CD27." (PMID 36385955, 2022). "As previously reported, in the cancer-immunity cycle, CD28: (CD80, CD86), CD40, CD27, HVEM, GITR: GITRL, ICOS, and TLR-2 are stimulatory factors, while TIM-3, PD-L1: PD-1, PD-L1: (CD80, CD86), CTLA-4: (CD80, CD86), BTLA, and LAG-3 are inhibitory factors." (PMID 35419462, 2022). "CD27, expressed by CD4, CD8 T lymphocytes, and NK cells, plays an important role in cancer immunotherapy." (PMID 35392242, 2022). "Agonistic antibodies to members of the TNFR-SF, such as 4-1BB, CD27, OX40 and GITR, are currently evaluated in cancer patients in numerous clinical trials." (PMID 36081508, 2022). "Second, most immuno-stimulators, such as MICB, MICA, CD80, ICOS, CD27, and various TNFSFs (all P < 0.05), were expressed at higher levels in PTPRD/PTPRT mutant cancers, compared with the WT." (PMID 36248841, 2022). "Thus, the expression and active engagement on T cells of CD27 by mAbs has the potential to positively affect adaptive immunotherapy against cancer, suggesting conversely that the pathological increase of T cells which lack CD27 expression could be a gradually increasing disadvantage." (PMID 36700229, 2022). "In hematological malignancies, cancer cells co-express CD70 and CD27 promoting stemness, proliferation and survival of malignancy." (PMID 34991665, 2022). "The qRT-PCR results of the clinical samples also showed that the mRNA expression of CD27, TNF, TNFRSF12A, TNFRSF13C, and TNFRSF9 is upregulated in cancer tissues, except EDA whose mRNA expression is downregulated in cancer tissues." (PMID 35392242, 2022). "Another indicator that shows PLAP CAR T cells are less differentiated than other groups is the high expression of CD27 and CD28 on PLAP CAR T cells, which can stimulate them against cancer cells." (PMID 36139135, 2022). "Significantly higher median serum levels of BTLA, CD27 and CD80 proteins were found in the group of high-grade carcinomas compared to the group of low-grade carcinomas (p = 0.01, p = 0.01, p = 0.03, respectively)." (PMID 35204342, 2022). "Increasing evidence supports that CD27 agonist antibodies, either alone or combined with PD1-blockade, can improve the therapeutic efficacy of cancer vaccines and immunotherapy in general." (PMID 34503105, 2021). "The CD27/CD70 axis can be targeted with antibodies and its blockade has potential for cancer immunotherapy." (PMID 34430923, 2021). "CD27 and its ligand CD70 are involved in the regulation of cellular immune responses to cancer and also enhance T cell proliferation and memory-cell formation." (PMID 33164640, 2020). "Take cancer type – CESC and gene – CD27, for example, the Cox proportional hazard model is given as follows: Surv(CESC) ~ Purity + B_cell + CD8+T-cell + CD4+T-cell + Macrophage + Neutrophil + Dendritic + NK_cell + mast_cell + CD27." (PMID 31358815, 2019). "Agonistic antibodies that activate CD27 and CD137 are in clinical trials for various cancers with anti-CD137 showing promising clinical activity." (PMID 28123897, 2016).
cancer (continued). "Various co-stimulatory TNFL/TNFR pairs, including CD40L/CD40, CD70/CD27, 4-1BBL/4-1BB, and OX40L/OX40, have gained prominence as possible targets for cancer immunotherapy, in particular with the aim of induction or (re)activation of antitumor T-cell immunity." (PMID 23840967, 2013). "In the section next I will discuss the biology of CD40L/CD40, CD70/CD27, 4-1BBL/4-1BB and OX40L/OX40 and highlight their current status for cancer immunotherapy." (PMID 23840967, 2013). "Further, ligand–receptor interactions differed: never‐smokers exhibited CD27+ B cell interactions via LGALS9–HAVCR2/CD44/CD45 and ANXA1–FPR1/FPR2, whereas smokers utilized CD74‐CXCR4/CD44 pathways linked to cancer progression." (PMID 41377765, 2025). "Costimulatory receptor molecules that mediate the signalling transduction pathways of T-cell proliferation, differentiation and activation, such as cluster of differentiation 27 (CD27) and 28 (CD28), have been proposed as important immunomodulation targets in cancer treatments." (PMID 40038352, 2025). "Some common and classical immune checkpoint genes such as LAG3, CD27, and TIGIT were most and significantly expressed in pattern B. The antitumor immune cycle works by activating and enhancing the immune system's ability to recognize and destroy cancer cells." (PMID 38322112, 2024). "The CD27 plays a significant role in CESC, HNSC, UCEC and UVM, and may be used as a therapeutic target for related cancers." (PMID 38169519, 2024). "Cluster of differentiation 27 (CD27) plays an important role in T-cell activation; due to binding with its natural ligand CD70, T-cell proliferation and differentiation to effector and memory T-cells is enhanced, making it a potential target in cancer therapy." (PMID 36157879, 2022). "Anti-CD27 mAb, varlilumab could enhance T cells expansion and reduce the frequency of Tregs in the PBMC of cancer patients." (PMID 35874720, 2022). "Since CD70 expression is absent during homeostasis, as opposed to CD27, it has great potential to exploit as a cancer-specific target." (PMID 34991665, 2022). "Previously, we reported that varlilumab, a CD27-targeting antibody, mediates Treg -preferential T cell depletion, CD8-T cell dominant costimulation, and systemic immune activation in hCD27 transgenic mice and cancer patients." (PMID 34028568, 2022). "In various types of cancer, findings between NNMT and immunostimulator gene expression showed a high connection (p < 0.05), including TNFSF13B, TNFRSF8, TNFSF14, IL6, IL2RA, CD80, CD27, and CD86." (PMID 36386816, 2022). "Although being well studied in T-cell immunity, the role of CD27 in cancer cells was not known well." (PMID 31358815, 2019). "For instance, the expression of CD27, CTLA4, PDCD1LG2; TNFRSF18 were all significantly inhibited across different types of TCGA cancers as can be seen in the comprehensive study of more than 10,000 tumors comprising 33 diverse cancer types by utilizing data compiled by TCGA92." (PMID 31358815, 2019). "Although the CD27 pathway has been studied less in this context, a number of studies support that this TNFR member may also be exploited for cancer immunotherapy." (PMID 26500773, 2015). "Our results reveal the efficacy of an optimized FRα-specific, CD27 costimulated RNA CAR T cell therapy platform and thus advocate for expedited clinical application of C4opt-27z CAR T cells across the broad range of FRα-expressing cancers." (PMID 26359629, 2015). "The greatest impact of CD27 was noted in vivo, where transferred CAR T cells with CD27 demonstrated heightened persistence after infusion, facilitating improved regression of human cancer in a xenogeneic allograft model." (PMID 23198862, 2013). "CD27 is a member of the tumor necrosis factor receptor superfamily and, in combination with its natural ligand CD70, activates the differentiation of T cells into effector and memory T cells and thus has potential as an immunomodulatory target in cancer therapy." (PMID 36686701, 2022).